EGFR (epidermal growth factor receptor)
Diseases named in the same sentence as EGFR in open-access papers (continued):
Sharing a sentence is not in itself a finding about the gene and the disease.
glioma (continued). "The neurotransmitter glutamate, which mediates synaptic transmission through the N-methyl-D-aspartate glutamate receptors 2A and 2B (GRIN2A and GRIN2B) that appear in the PCST network, can promote glioma cell growth, and this pro-proliferative effect in U87MG cells is due to EGFR signaling." (PMID 23408876, 2013). "Nimotuzumab is a humanized monoclonal antibody that recognizes the EGFR extracellular domain and reaches Central Nervous System tumors, in nonclinical and clinical setting." (PMID 23782513, 2013). "Another study revealed a positive correlation between CRNDE levels and epidermal growth factor receptor (EGFR) gene amplification, associated with EGFR overexpression, in high grade oligodendrogliomas, a type of glioma in which CRNDE is not always upregulated." (PMID 23226159, 2012). "Compared to a glioma sample with an amplified EGFR, none of the analyzed meningiomas showed EGFR gene amplification." (PMID 22623992, 2012). "Either EGFR-targeting monoclonal antibody or inhibition of tyrosine kinases activity in glioma patients produced minimal tumor response and no improvement in overall survival." (PMID 21955618, 2011). "By contrast, glioma regions primarily comprised of eGFP-negative recruited cells frequently expressed EGFR or IGFR and not PDGFR." (PMID 21754979, 2011). "While these experiments did not directly compare transit amplifiers and neural stem/progenitor cells, they can confirm the ability of non-self renewing cells to initiate PDGF-induced gliomas, unlike the EGFR-induced case." (PMID 21931722, 2011). "In the two PTEN null/mutant human glioma cell lines (U251HF and SNB19) under serum-free conditions, the suppressive effect of EFEMP1 on AKT phosphorylation was seen 24 hours after the treatment, while total EGFR reduction occurred a day later." (PMID 21955618, 2011). "Surprisingly, the kind of cells surviving in vitro in case of gliomas presenting EGFR amplification has not been defined in spite of years of investigation." (PMID 21326241, 2011). "Although a number of point mutations are also observed in the EGFR gene, the activating mutations in the ATP binding domain observed in lung cancer (NSCLC) are not observed in gliomas." (PMID 24212656, 2011). "We show that constitutive coactivation of EGFR-Ras and PI3K signaling in Drosophila glia and glial precursors gives rise to neoplastic, invasive cells that create transplantable tumor-like growths, mimicking human glioma, and mirroring mouse glioma models." (PMID 19214224, 2009). "To address the function of EGFR-Ras and PI3K in glioma, we analyzed the genetic basis of glial pathogenesis in our repo>dEGFRλ;dp110CAAX model, as this model shows robust neoplasia, similarity to human tumor genotypes, and sensitivity to dEGFR and dPTEN gene dosage (data not shown)." (PMID 19214224, 2009). "EGFR-Ras and PTEN-PI3K signaling regulates many developmental processes in these cell types, particularly proliferation and self-renewal, which are also properties of glioma cells." (PMID 19214224, 2009). "We found that constitutive coactivation of the EGFR-Ras and PI3K pathways in Drosophila glia gives rise to highly proliferative and invasive neoplastic cells that create transplantable tumor-like growths, mimicking human glioma." (PMID 19214224, 2009). "Epidermal growth factor receptor (EGFR) is a 170 kDa transmembrane tyrosine kinase that binds to EGF and mediates signalling pathways leading to survival, proliferation, migration and invasion of glioma cells." (PMID 19018263, 2008). "It is currently under investigation whether versican V1 and TGF-β2 can interact with each other also in regard of their activated signaling cascades, such as the EGFR- and integrin-mediated ERK pathways, enhancing the malignant progression of glioma." (PMID 17453002, 2007).
glioma (continued). "Overall, our results suggest that multiple pathways of EV biogenesis may operate in glioma cells resulting in formation of complex EV landscapes consisting of EGFR-positive and EGFR-negative EV subsets." (PMID 41953752, 2026). "Moreover, USP25 enhances EGFR expression through cytosolic METTL3, driving glioma progression." (PMID 41321637, 2025). "Currently, pan-targeted anti-angiogenic tyrosine kinase inhibitors (TKIs) targeting EGFR mainly act on the extracellular domain of EGFR, blocking intracellular signaling pathways such as MAPK and PI3K in tumor cells to control tumor growth, which is the direction of anti-EGFR treatment for gliomas." (PMID 40061015, 2025). "An EGFR-directed ADC, depatuxizumab mafodotin (Depatux-M, formerly ABT-414), which uses the mAb806 antibody against a tumor-specific EGFR epitope, demonstrated potent anti-tumor effects in preclinical glioma models with EGFR overexpression, EGFR amplification, or EGFRvIII mutations." (PMID 40918539, 2025). "For EGFR amplification in IDH‐wildtype, the best and concordant models showed AUCs of 0.821 (95% CI: 0.761–0.881) and 0.746 (95% CI: 0.675–0.817) in newly diagnosed gliomas, but poor performance in recurrent tumors with AUCs of 0.503 (95% CI: 0.34–0.665) and 0.518 (95% CI: 0.357–0.678)." (PMID 40197845, 2025). "They demonstrated that the constitutive coactivation of EGFR-Ras and PI3K signaling in Drosophila glia and glial precursors leads to neoplastic glial proliferation and transplantable tumor-like growths, which recapitulate the characteristics of human GBM and animal glioma models." (PMID 40806617, 2025). "Consequently, a treatment plan that combines temozolomide with EGFR and TNF inhibition may represent an effective therapeutic approach for gliomas expressing CSMD1." (PMID 38561856, 2024). "The exact effect of the EGFR on the efficacy of glioma PDT has not yet been thoroughly investigated; however, the available work suggests that the EGFR may contribute to resistance to PDT, as it does in other cancers." (PMID 39201395, 2024). "In grade 3 gliomas (n = 26), 22 cases (84.6%) showed IDH1 mutations, and no EGFR-amp was observed." (PMID 38893240, 2024). "Tumor-associated microglia promoting glioma cell invasion can be mediated by CSF-1R signaling on gliomas, a pathway involving CSF-1 signaling via ERK that upregulates the expression of dual-regulatory proteins (AREG) in microglia, which are ligands for epithelial growth factor receptor (EGFR)." (PMID 37700840, 2023). "For example, glioma cells transfer extracellular vesicles containing the oncogenic receptor EGFR VIII to adjacent glioma cells lacking this receptor, thereby activating the AKT pathway in adjacent glioma cells, giving these cells the ability to grow independently of anchoring." (PMID 37305043, 2023). "While previous investigations have failed to extend glioma patient survival using either EGFR-targeting agents or inhibitors of PI3K pathway components, we believe our findings are meaningful in designing clinical trials with osimertinib and MK-2206 for osimertinib-resistant GBM patients." (PMID 37669963, 2023). "Moreover, EGFR stimulates cell migration through receptor phosphorylation and subsequent activation of downstream signaling pathways, including the AKT and MAPK pathways, to support glioma growth." (PMID 37408388, 2023). "Our cases do not exactly fit in this model, but it is noteworthy that EGFR alteration may influence the immune landscape of gliomas and provide a stratification scheme to find patients who are sensitive to immunotherapy." (PMID 37537946, 2023). "To determine the clinical significance of EGFR/EZH2 dependent NFAT5 lysine methylation in glioma, we performed IHC analysis to examine the expression and correlation between EZH2 pS21 and Me3-NFAT5 K668 as well as EGFR pY1068 levels in 83 human glioma specimens." (PMID 37429858, 2023).
glioma (continued). "Integrated analysis of molecular key hallmarks in glioma (IDH, TERT, MGMT methylation, and LOH 1p/19q) and EGFR amplification showed that EGFR amplification is a phenomenon that can be predominantly found in IDH wildtype and TERT mutated gliomas, as well in gliomas without LOH 1p/19q." (PMID 35453544, 2022). "Second, we could not classify the IDH-wt glioma further due to the missing molecular information (such as the TERT promoter mutation and EGFR amplification)." (PMID 35741587, 2022). "Indeed, an addition of the EGFR inhibitor, gefitinib, alone or simultaneously with interferon treatment, performed in our work, demonstrated developing resistance to VSV for two otherwise sensitive standard cell lines and three primary glioma cultures." (PMID 35563635, 2022). "Despite the prevalence and apparent reliance on PI3K signaling in glioma, PI3K inhibitors exert cytostatic rather than cytotoxic effects in glioma cell lines and xenografts even when combined with inhibitors of the epidermal growth factor receptor (EGFR) and mTOR." (PMID 35163279, 2022). "Among these signaling pathways, epidermal growth factor receptor (EGFR), insulin-like growth factor receptor (IGFR), tropomyosin receptor kinases (Trk), transforming growth factor-β (TGF-β) and the Hippo pathway have been shown to regulate anoikis resistance in glioma." (PMID 36046036, 2022). "Furthermore, overexpression experiments suggest that TRIM11 exerts its oncogenic function in gliomas via EGFR/MAPK signaling and most likely without involvement of the PI3K/Akt pathway." (PMID 36139694, 2022). "According to the analysis in regard to distinct molecular markers, we found that the mRNA expression signature was significantly elevated in IDH wildtype tumors, cases without 1p/19q codeletion, gliomas with homozygous loss of CDKN2A/B and in the EGFR amplification group." (PMID 36187350, 2022). "According to analysis of individual molecular markers, we found a significantly higher heme biosynthesis mRNA expression signature in gliomas with IDH wildtype (p < 0.0005), without 1p19q codeletion (p < 0.0005), with homozygous CDKN2A/B loss (p < 0.0005) and with EGFR amplification (p = 0.001)." (PMID 36187350, 2022). "Evidence has shown that several molecules such as Ki-67, epidermal growth factor receptor (EGFR), vascular endothelial growth factor (VEGF), O-6-methylguanine-DNA methyltransferase (MGMT), and hypoxia-inducible factor 1-alpha (HIF-1α) play important roles in the growth of glioma." (PMID 36591483, 2022). "Moreover, miR-155, miR-181a/b and miR-410 may participate in the molecular mechanism of high-grade glioma by interaction PDCD4, WNT5A, MET, and EGFR." (PMID 35646622, 2022). "To understand whether the increased surface availability and constitutive endocytosis of EGFR in spheroids translated into an increased ADC effect, we next treated 2D and 3D glioma cultures with an anti-EGFR antibody precomplexed with a secondary antibody-monomethyl auristatin F toxin conjugate." (PMID 35217608, 2022). "For glioma cell lines U87 ΔEGFR, and 251 EGFR VIII, we observed that erlotinib nor luteolin alone at the concentrations tested did not induce significant apoptosis as measured by the expression of cleaved PARP, cleaved caspase, Bcl-xL using Western blot analysis." (PMID 36199696, 2022). "Of all analyzed TERT wildtype gliomas, none show an EGFR amplification." (PMID 35453544, 2022). "In addition, strong expression of Ki-67, partial expression of EGFR and VEGF, and weak expression of MGMT and HIF-1α was oberserved on immunohistochemical staining, These supplementary characteristics will make GSC glioma model a better test platform for glioma." (PMID 36591483, 2022). "TNFα can facilitate angiogenesis by increasing epidermal growth factor receptor (EGFR) activity; it induces immune cell suppression through the activation of the NF-κB and STAT3 pathways, and decreases the expression of the tumor-suppressor gene PTEN in glioma." (PMID 35626018, 2022).
glioma (continued). "In glioma cells, LPCAT1 induces the conversion of lysophosphatidylcholine from an unsaturated to a saturated state accompanying the remodeling of membrane lipids, resulting in the activation and recruitment of the EGFR pathway, which, in turn, further promotes the biosynthesis of LPCAT1." (PMID 35399731, 2022). "Despite the growing interest of the scientific community in understanding LRP-1 functionalities in tumour progression and resistance to treatments, the role of LRP-1 in the regulation of EGFR trafficking and glioma cell resistance to TKI had never been addressed so far." (PMID 34831480, 2021). "Finally, EGFR (epidermal growth factor receptor) expression, without loss of PTEN (phosphatase and tensin homolog), explains the sensitivity of gliomas to tyrosine kinase inhibitors." (PMID 33916593, 2021). "Therefore, molecules with high selectivity to EGFR mutant genes and high penetration through the BBB may be effective for the treatment of glioma." (PMID 34635007, 2021). "Glioma patients without EGFR amplification had longer overall survival." (PMID 33959491, 2021). "miR-1 could decrease the expression of EGFR, PCR1, PCR2, and p-JNK by targeting ANXA2 and Met, thus inhibiting the growth of glioma cells and tumor angiogenesis and reducing the invasiveness of glioma cells." (PMID 34540663, 2021). "Another study distinguished between glioma with amplified and non-amplified EGFR under DWI." (PMID 34422648, 2021). "Aberrantly overexpressed epidermal growth factor receptor (EGFR) in GBM results in poor prognosis, low survival rates, poor responses to therapy and recurrence, and therefore EGFR-targeted therapy stands out as a promising approach for the treatment of gliomas." (PMID 34681605, 2021). "However, analysis of gene expression in EGFR-low human glioma tissue samples did not reveal a correlation between upregulation of RRAD and poorer prognosis." (PMID 33980886, 2021). "Furthermore, glioma patients without EGFR amplification and CDKN2A deletion had the best prognosis than glioma patients with EGFR amplification or CDKN2A deletion or with both alterations in the MSKCC datasets." (PMID 33959491, 2021). "Treatment of EJ28Luc bladder cancer cells, but not of the LN18 glioma cells with 213Bi-anti-EGFR-MAb resulted in decreased incorporation of 13C-labelled glucose into amino acids derived from glycolytic and TCA cycle intermediates, indicative of an early treatment response." (PMID 33737524, 2021). "As research continues, an increasing interest in the function of CRNDE in glioma reveals that CRNDE could modulate glioma cell growth and invasion with EGFR activation and through mTOR signaling, and promote malignant progression by attenuating miR-384/PIWIL4/STAT3 axis in GBM." (PMID 34454479, 2021). "However, the activity of EGFR-TKIs is suboptimal for CNS cancer treatment, as EGFR-TKIs do not readily cross the blood–brain barrier (BBB)." (PMID 34359582, 2021). "Besides, we analyzed the expression of glioma-associated genes in homogeneous groups, including subgroups of different cell origins, and different molecular subtypes, such as EGFR-positive and EGFR-negative gliomas." (PMID 32819307, 2020). "Indeed, co-mutant EGFR and SETD2 are common in glioma and pan-cancer, suggesting that SETD2-mutant cancer might have evolved a unique dependence on EGFR signaling." (PMID 32824422, 2020). "In this study, we develop a nanoinhibitor, BIP-MPC-NP, which can simultaneously mitigate the crosstalk between EGFR and MET signaling pathways contributing to the TMZ resistance by conjugating Inherbin3 and cMBP on the surface of NHS-PEG8-Mal modified MPC-nanoparticle in glioma." (PMID 32001707, 2020). "Still, there is no study that has analyzed the EGFR promoter in human glioma samples." (PMID 33321953, 2020).
glioma (continued). "In an unselected population without known IDH status, lack of EGFR amplification may be a surrogate of an IDH-mutant glioma, which may lead to the observation that a lack of EGFR amplification is associated with better prognosis." (PMID 33235995, 2020). "Many of the soluble factors involved in GAM-glioma crosstalk have been identified, such as epidermal growth factor (EGF), which is released by MG and stimulates GBM cell migration and invasion via the commonly upregulated epidermal growth factor receptor (EGFR) on glioma cells." (PMID 33117364, 2020). "We showed that CDK5 regulates glioma tumorigenicity by promoting TRIM59 nuclear translocation via PIN1/importin α5 axis, leading to STAT3 signaling activation, and demonstrate that CDK5 mediates EGFR-stimulated STAT3 signaling through activation of the TRIM59/mH2A1 axis in GBM." (PMID 31488827, 2019). "They reported EGFR Affibody–IR700Dye conjugate specific uptake in vitro enabled imaging of EGFR expression in an orthotopic brain tumor model, and an NIR-PIT study in vivo demonstrated therapeutic efficacy of the conjugate in a subcutaneous glioma xenograft model." (PMID 31757056, 2019). "In addition, the combination of EGFR and VEGFR genes showed clinical relevance in glioma patients." (PMID 31074391, 2019). "It is unknown whether CAR T cells can control infiltrative gliomas without injuring the surrounding brain parenchyma, and whether ablation of EGFR-expressing glioma cells will provide a selective survival advantage for EGFR-negative malignant cells." (PMID 31903167, 2019). "However, despite the important role of EGFR in glioma development, suitable EGFR- targeted therapies for glioma have not been developed." (PMID 29732009, 2018). "Exon-4-deleted EGFR (de4 EGFR) was detected in 27% of PCa samples but not in normal tissue, and its overexpression reduced E-cadherin expression and increased metastatic potential in a glioma cell line." (PMID 29535823, 2018). "In order to explore whether or not it has a synergistic effect with the thermotherapy of glioma, EGFR-targeted composite MNPs are constructed using MNPs as a carrier and C225 as a target molecule, where C225 is fixed on the MNPs surfaces." (PMID 29652919, 2018). "To understand the mechanism of ENb-TRAIL function, we compared the efficacy of ENb-TRAIL with EGFR-targeted therapeutics (monoclonal antibody Cetuximab, ENb or Erlotinib) or with TRAIL alone at different doses in HT29 (colon), Calu1 (lung), and LN229 (glioma) tumor lines." (PMID 28572590, 2017). "Importantly, EGFR CNG significantly shortened median survival times of glioma patients regardless of gender, tumor grade and therapeutic regimens." (PMID 29190914, 2017). "High levels of EGFR (positive in > 10% of the total living cells) in the CD45−CD105− cells was detected in 6 of 6 RMPAhigh and 13 of 16 RMPAlow gliomas analyzed; and high PLXNB2 expression in the CD45−CD105− cells was detected in 5 of 6 RMPAhigh and 11 of 16 RMPAlow gliomas analyzed." (PMID 27385209, 2016). "Moreover, BRAFV600E inhibition of glioma cells with the vemurafenib tool compound PLX4720 releases a negative feedback loop that is placed on EGFR signaling by BRAFV600E." (PMID 27713119, 2016). "However, unsupervised principle component analysis of the global transcriptome data showed similar transcriptomic profiles between the RMPAhigh gliomas with or without EGFR alterations." (PMID 27385209, 2016).